CTLA4 (cytotoxic T-lymphocyte associated protein 4)
Diseases named in the same sentence as CTLA4 in open-access papers (continued):
Sharing a sentence is not in itself a finding about the gene and the disease.
tumor (continued). "By using anti-CTLA-4 mAb to specifically block the B7-1/CTLA-4 interaction, a significantly higher rate of rejection of B7-1+ C1498 tumor was observed, indicating that B7-1 delivered negative signal to T cell immunity via CTLA-4." (PMID 31186046, 2019). "Recent studies have demonstrated that tumor-derived Th17 cells produce low levels of TGF-β and IL-10 after stimulation with anti-CD3 in vitro and express CTLA4, FoxP3, and CD25 as Treg cell markers, while they do not suppress tumor progression." (PMID 31024835, 2019). "The right flank tumor was then injected with 30μg of the TLR9 agonist ODN1826 or PBS on days 3, 6 and 9 with or without concordant injection of 100μg of the CTLA-4 blocking antibody 9H10 systemically." (PMID 31771649, 2019). "BC was considered a non-immunogenic tumor entity before analyzing TIL infiltration At current, the application of T cell-mediated immunotherapy of CTLA-4 and PD-L1 inhibitors in combination with standard of care BC therapy in BC patients is quite promising." (PMID 30717704, 2019). "In tumor bearing mice, crizotinib increased the expression of the PD-1 (and LAG-3 but neither CTLA-4 nor TIM-3) on circulating CD4+ or CD8+ T lymphocytes." (PMID 30940805, 2019). "The combination of SLC-PDL1 and SLC-CTLA4 led to significantly decreased tumor volumes, compared to each monotherapy, in both the CT26 and A20 tumor models, although comparison with the combination of systemic PD-L1 and CTLA-4 blockade was not performed." (PMID 31373327, 2019). "Similar expression patterns were seen for tumor-infiltrating CD4 T cells, but there was a higher frequency of Tregs expressing CTLA-4 compared with non-Treg CD4 T cells." (PMID 31804466, 2019). "Values of few populations (CD45RO+ in Frozen PBMC, and CD45+, CD3+TIGIT+, CD3+CTLA4+, and CD3+CD28+ in tumor biopsies) did not give rise to statistically equivalent results using equivalence test." (PMID 31165047, 2019). "This lack of antitumor efficacy is similar to the lack of responses observed in KPC tumor bearing animal treated with anti-PD1 and/or anti-CTLA-4 mAb." (PMID 30959852, 2019). "However, simultaneous inhibition of the B7-CTLA-4 pathway by an anti-CTLA-4 antibody may increase the number of activated CD8+ T cells in lymph nodes, followed by an increase in the number of activated CD8+ T cells infiltrating into tumoural tissues, thereby enhancing their antitumour effects." (PMID 31671581, 2019). "In fact, our study shows that CTLA-4 is expressed by non-Treg activated T cells including resting Tmem and FOXP3− Tfh-like effector T cells in the tumor microenvironment." (PMID 30061879, 2018). "Other groups have provided evidence that anti-CTLA-4 antibodies can directly engage with CTLA-4+ tumor cells to drive ADCC, but this is unlikely to fully explain the profound anti-tumor effects of CTLA-4 based CI therapy." (PMID 30319637, 2018). "Using genetic model in which the anti-CTLA-4 antibodies are unable to engage more than 50% of CTLA-4, we demonstrated that saturating binding of CTLA-4 is not necessary for tumor rejection." (PMID 29713453, 2018). "Preclinical evaluation of checkpoint inhibitors in PDA therapy has been considered; however, as PDA is a non-immunogenic tumor, monotherapy blocking of the PD1/PDL1 axis or CTLA4 have not been successful." (PMID 29301364, 2018). "Treatment of MDA-MB-231-luc-bearing mice with either a-CTLA-4 alone or the combination of a-CTLA-4 and a-PD-1 mAbs failed to inhibit tumor growth or lung metastases compared with untreated animals." (PMID 29467463, 2018). "In line with this and unlike reported for basal squamous tumors in the TCGA publication, CDKN2Ahigh tumours also do not show an elevation of PDCD1, CD274 and CTLA4 expression." (PMID 30258198, 2018). "We found that PD-1, CTLA-4, TIM-3, and LAG-3 were upregulated in tumor tissue, compared with normal tissue, while there was no change in PD-L1 and TIGIT." (PMID 29983831, 2018).
tumor (continued). "For both Tim-3 and CTLA-4, there was a correlation between the frequency of CD8 and non-CD8 T cell expression of these markers in tumour tissue (data not shown)." (PMID 28423034, 2017). "Interestingly, it has been suggested that a pre-existing immune-active tumor microenvironment is what mediates the anti-tumor activity of CTLA-4 blockade; hence, one may speculate that stromal CTLA-4 expression may have potential as a predictive marker for anti-CTLA-4 treatment in NSCLC patients." (PMID 28707078, 2017). "In this context, it should be noted that recent work suggests that the therapeutic efficacy of CTLA-4 antibodies may not be primarily due to neutralization of CTLA-4-mediated T cell inhibition but is owed to its ability to deplete regulatory T cells in the tumor microenvironment." (PMID 28588576, 2017). "Basic immunologic observations support the notion that PD-1/PD-L1 pathway, CTLA-4, and IDO regulate T-cell responses and promote tumor immunosuppression through overlapping as well as non-redundant mechanisms." (PMID 27756892, 2017). "Aside CTLA-4 expression, there were no clear differences in the expression of CD28, CD45RO, and CD62L between PD-1+ cells in tumor infiltrating CTLs at the tumor site and whole CD8+ T cells." (PMID 29163789, 2017). "The proportion of CD4+ cells among CTLA-4+ T cells in non-cancerous mucosa was decreased compared to PBMC HNSCC (51.0 ± 18.8% vs. 69.3 ± 14.6%; p < 0.05), but not compared to tumor tissue." (PMID 28574843, 2017). "Additionally, our observations imply that MPNST and plexiform tumors may benefit from CTLA-4 immune checkpoint blockade therapy, with the majority of the CTLA-4 expression detected likely coming from the tumoral microenvironment rather than the tumor cells themselves." (PMID 29137242, 2017). "Different modes of immune evasion were seen across 12 tumours with up-regulation or consistent expression of CD47, unlike other immune evasion genes such as PDL1, FUT4, CTLA4 and BTLA which were downregulated in a few samples." (PMID 28886030, 2017). "Tumor infiltration of CD8+ T-cells was analyzed more frequently, showing correlations to response in two out of four PD-1 analyses but in none of the four CTLA-4 ICI analyses." (PMID 29034210, 2017). "Consistent with the DASL data, the CTLA4 and LCK genes in TCGA RNAseq data demonstrated up-regulated expression in tumor compared to matched normal in the young cohort but not in the older cohort." (PMID 28027300, 2016). "These authors confirmed the importance of T cells by combining fractionated RT and CTLA-4 blockade that resulted in CD8 T cell-mediated tumour regression of irradiated and distant non-irradiated tumours." (PMID 27427766, 2016). "CTLA-4 and CD8+ TILs (tumor infiltrating lymphocytes) expressions were not statistically significant." (PMID 27741514, 2016). "In contrast, while mice treated with PLGA-ICG-R837-based PTT to ablate their primary tumours showed delayed metastases, the group with PLGA-ICG-R837-based PTT together with CTLA-4 blockade therapy showed nearly no metastasis." (PMID 27767031, 2016). "In contrast, the preoperative serum levels of CTLA‐4, B7‐H3, CD28, CD80, and CD86 were not correlated with tumor biological characteristics in this study." (PMID 27292320, 2016). "While none of our immunotherapy approaches (including α-CTLA-4/α-PD-1, α-CD137/α-PD-1, IL-2) possessed any anti-tumor efficacy themselves, only α-CD137/α-PD-1 enhanced the anti-tumor effect of SBRT." (PMID 27160390, 2016). "In our experiments, for mice with primary tumours removed by surgery, either PLGA-ICG-R837 injection alone or anti-CTLA-4 treatment alone failed to promote CD8+ CTL infiltration into the secondary tumours." (PMID 27767031, 2016). "We find that ALK+ and ALK− ALCL share common DNA methylation changes for genes involved in T cell differentiation and immune response, including TCR and CTLA-4, without an ALK-specific impact on tumor DNA methylation in gene promoters." (PMID 27705804, 2016).
tumor (continued). "The knock-down of CTLA-4, albeit partial, was evidently sufficient to trigger enhancement of 19z1-CD80+ T cells’ anti-tumor properties, although not modifying those of 19-28z+ T cells." (PMID 26110267, 2015). "Moreover, one of the first studies of the addition of CTLA-4 antibody failed to increase the clinical response to a Granulocyte/Macrophage/Colony Stimulating/Factor (GM-CSF) gene-transduced tumor cell vaccine (GVAX) while augmenting the tumor destruction by patient T cells." (PMID 26343195, 2015). "B7H1 is considered a better target than another negative co-stimulating molecule, CTLA-4, because the distribution of B7H1/PD-1 axis is within the tumor microenvironment more selectively." (PMID 26284927, 2015). "On the other hand, we found that CTLA-4 was not expressed in the cultured CT26 cells, although it was strongly expressed in the CT26 tumor tissues." (PMID 25365349, 2014). "For example, in the immunotherapy using tumor peptide CTL or antibodies against PD-1 or CTLA4, the target is the CD8 killer T cell, which kills MHC positive but not negative tumor cells, resulting in tumor recurrence." (PMID 24348476, 2013). "Perhaps the simplest explanation is that the anti-CTLA-4 mAb migrates to multiple sites of CTLA-4 expression (i.e. the gut), and that expression of CTLA-4 on tumor-specific T cells is not particularly robust until after antigen-specific vaccination." (PMID 23557194, 2013). "Furthermore, in mice concurrently challenged with two tumors, treatment of one tumor with local RT in combination with systemic administration of anti-CTLA-4 could induce significant growth delay in the second tumor that did not receive local RT; a process referred to as the abscopal effect." (PMID 23087904, 2012). "Anti 4-1BB treatment, with or without CTLA-4 blockade, induced approximately 75% of CD8+ and 45% of CD4+ effector T-cells in the tumor to express the killer cell lectin-like receptor G1 (KLRG1)." (PMID 21559358, 2011). "Similarly in control KPC-tumor-bearing mice, PD1 and CTLA4 inhibition slightly though not significantly decreased tumor burden, but the checkpoint blockade in iCoup mice further inhibited tumor growth significantly." (PMID 40796746, 2025). "Together, these results indicated that IFNγ is essential for the pruning of CD45−CD31high tumor endothelial cells and the accumulation of CD8+ T cells into tumors during anti-CTLA-4 therapy but not for the formation of TA-HEVs or the modulation of their phenotype." (PMID 40460830, 2025). "DEFB1 inhibits tumor invasion and migration in OSCC, and CTLA4, a negative regulator of T cell activation, has shown efficacy in boosting anti-tumor immunity when targeted with CTLA4 inhibitors." (PMID 39857718, 2025). "Similarly, a phase I trial assessing ipilimumab, an anti-CTLA-4 antibody, in pediatric solid tumors, including RMS cases, showed no objective tumor regressions." (PMID 41007114, 2025). "Immune checkpoint molecules such as PD-1 and CTLA-4, along with their respective inhibitors (anti-PD-1/anti-PD-L1 and anti-CTLA-4), enhance anti-tumor immunity by attenuating negative feedback mechanisms that normally restrain immune activation at checkpoint interfaces." (PMID 41462587, 2025). "Moreover, inhibiting adrenergic neuronal stress lowers the expression of co-inhibitory receptors—like CTLA-4, PD-1, LAG-3, and Tim-3—on CD8+ T cells located in non-irradiated regions of the tumor." (PMID 38567163, 2024). "In contrast, patients with higher and lower than average levels of CTLA-4 expression demonstrated mean PFS times of 36.063 ± 7.923 months and 50.841 ± 13.335 months, respectively (p = 0.845); hence, CTLA-4 was not an indicator of tumor progression." (PMID 38672574, 2024). "Together, CTLA4 may be a biological characteristic of THCs; while, CD3 proteins may represent immune cells (non-hybrid cells) in tumor tissues." (PMID 39499374, 2024).
tumor (continued). "CTLA4 provides a negative modulatory signal to T cells interacting with its primary ligands, CD80 or CD86, on an antigen-presenting cell, and is well described as a key component of tumor immune evasion." (PMID 39478117, 2024). "Additionally, we found that, compared to sham controls, CD45hi/CD11bhi cells from tumor-bearing mice exhibited upregulated expression of several immune checkpoints, including VISTA, CD80, PD-L1, and CTLA-4 but not Tim-3." (PMID 39123357, 2024). "Unlike PD-1 and CTLA-4, VISTA expression is prominent in myeloid cells, including neutrophils, tumour-infiltrating leukocytes and myeloid-derived suppressor cells (MDSCs), which play a critical role in suppressing tumour-specific T-cell responses." (PMID 39060374, 2024). "Interestingly, the delayed depletion selectively reduced tumor protection from IVAX and CTLA-4 blockade but not CTLA-4 alone." (PMID 38517331, 2024). "Importantly, the Treg population in the tumor had, overall, a CD44hiCD62L– effector phenotype, but given the low levels of ICOS and CTLA-4 and the lack of proliferation, they clustered as cTregs." (PMID 38349740, 2024). "Indeed, PCa is defined as a “cold” tumor because of insufficient intratumoral CD8+ T cell infiltration/activation coupled with the lack of success of anti–PD-1 and/or anti–CTLA-4 therapy." (PMID 36626227, 2023). "The CONDOR trial was a randomized, phase II study that assessed durvalumab monotherapy, tremelimumab (a CTLA-4 monoclonal antibody) monotherapy, and combination tremelimumab and durvalumab in 267 patients with refractory RM HNC and low/negative PD-L1 tumor expression." (PMID 37046621, 2023). "Notably, we previously reported that RMC tissues upregulated expression of immune-checkpoint receptors such as PD-1, CTLA-4, and LAG3, although PD-L1 expression in tumor cells was notably heterogeneous." (PMID 37568622, 2023). "Furthermore, the expression of CTLA-4 in the sorted T cells increases slightly in the CAP-treated group, in a manner similar to the expression of its ligand, CD80, in the tumor cells; however, the difference is not significant." (PMID 37189453, 2023). "Notably, unlike its pro-tumor effects on MDSCs, EZH2i disrupt TREG biology and synergizes with anti-CTLA4 ICB in murine models." (PMID 38044445, 2023). "However, these previous studies do not discuss the interaction between CTLA4 + T cells and S100A4 in the tumor microenvironment of TNBC." (PMID 37838657, 2023). "Furthermore, while the combination of CTLA-4 and PD-1 blocking antibodies did not have antitumour effects by themselves, combining them with TDM-1 resulted in potent anti-tumour activity yielding a near 100% cure rate." (PMID 36046842, 2022). "However, one hypothesis suggests that CAR-T cell therapy for most tumor cells with unexpressed targeted antigen is unlikely to be successful unless combination strategies that enhance bystander effects are applied, and neither anti-PD-1/CTLA-4 antibodies stir bystander effects." (PMID 36168626, 2022). "Transfer of a small number of CD4 T cells into lymphopenic mice, in combination with CTLA-4 blockade or CD137 agonist immunotherapy, resulted in potent rejection of large vascularized tumours, independent of other immune cells and in an MHCII-restricted manner." (PMID 35572552, 2022). "When combined with anti-CTLA-4, the PIC + RT in situ vaccination enabled greater tumor response and improved survival as well as tumor-specific immune memory and robust systemic anti-tumor immunity at tumors not directly treated by RT or PIC injection." (PMID 35999216, 2022). "Interestingly, we found a significant negative correlation between tumor weight and CD8+ Teffs, CD4+ Teffs, cDC2, or neutrophil frequency in mice treated with CTLA-4 blockade in combination with 7HP349." (PMID 35552271, 2022).
tumor (continued). "However, LEM significantly reduced PD-L1 expression on tumor cells, and tumor-infiltrating monocytic MDSCs (M-MDSCs), PMN-MDSCs, and CD11b+CD11c+ double-positive cells, with or without anti–CTLA-4 therapy." (PMID 35239514, 2022). "However, CTLA-4 expression, on tumor-specific CD8+ T cells and CD4+ Foxp3+ Tregs was not affected by anti-CD73 treatment in this tumor." (PMID 35711418, 2022). "Furthermore, anti-CTLA-4 monotherapy did not affect the number of SPAS+ T cells in the spleen, tumor, or NLT at the experimental tumor endpoint." (PMID 34162858, 2021). "The TGFβ1 level (lower or higher than the median) in tumor stroma was positively associated with that of PD-L1 in tumor stroma and tumor (P ≤ 0.001, R = 0.428, 0.388), and CTLA4 in tumor stroma (P ≤ 0.001, R = 0.350), but not CD8 or FoxP3 in tumor stroma (P = 0.970; 0.249, respectively)." (PMID 34095135, 2021). "This suggests that, while 90Y-NM600-treated tumor cells can activate IFN-gamma production independent of tumor cell expression of STING, the beneficial effects of anti-CTLA-4 in combination with 90Y-NM600 may be STING-dependent." (PMID 33995649, 2021). "Furthermore, unexpectedly, the depletion of CTLA-4 from a Treg cell population of adult mice conferred resistance to autoimmune encephalomyelitis (EAE) and did not enhance anti-tumor immunity." (PMID 33809974, 2021). "At the same time, the expression of PD-1, Lag-3, CTLA-4, Tim-3, and Granzyme B on Tregs from cryo-thermal treated mice was decreased, and the expression of perforin, T-bet and IFN-γ in Tregs was not different from that in Tregs from tumor-bearing control mice." (PMID 34576115, 2021). "Interestingly, unlike single-agent treatment with anti-PD-1/PD-L1 or anti-CTLA-4 antibodies, both anti-CD40 and OX40 antibodies as single agents have demonstrated efficacy in Pan02 tumor-bearing mice, in both subcutaneous and orthotopical models." (PMID 33503832, 2021). "Patients with clear cell histology appear to have a more favorable response to anti-CTLA-4 therapy as compared with non-clear cell histologies owing to a pre-existing TME with higher IFN-γ expression, favorable increase in tumor-infiltrating immune cells and, an increase in TLS." (PMID 34737281, 2021). "Anti-CTLA-4 treatment resulted in the eradication of tumors in four out of five mice, whereas anti-PD-1 temporarily inhibited YTN16 tumor growth but failed to eradicate the tumor in four out of five mice." (PMID 35008270, 2021). "In contrast, in the majority of cases, sole application of any of the anti-CTLA-4, anti-PD-1, and/or anti-HSP90 molecules used either alone or in combination with each other did not affect the clonogenic potential of the lung-derived tumor cells." (PMID 34208396, 2021). "Interestingly, in a model of glioma, IL13-Ra2-targeted CAR T cells engineered to secrete an anti-CTLA-4 minibody, but not anti-PD1 or –TIM3, were able to significantly control tumor growth." (PMID 32764348, 2020). "Tumor-infiltrating immune cells comprise a previously unrecognized diversity of cell types, including CD8+ T cells predominantly expressing the checkpoint marker LAG3, rather than PD1 or CTLA4." (PMID 31980621, 2020). "Furthermore, we observed significant CTLA4 expression in CT26 in vivo tumor samples and on some tumor infiltrating NK cells based on single-cell RNA-Seq (data not shown)." (PMID 31898484, 2020). "Since the lack of CD28-mediated second signal in presence of CTLA-4 results in T cell anergy, the inhibition of CTLA-4 receptor (by means of the use of specific monoclonal antibodies) allows T cell activation, thus restoring anti-tumor immunity." (PMID 33162990, 2020). "A new study revealed that Fc-engineered anti-CTLA-4 mAb (with high ADCC activity) was able to increase the anti-tumor immunity in vitro in humans and in vivo in mice by decreasing CTLA-4hi effector Tregs, whereas anti-CTLA-4 mAbs with much less or no ADCC activity did not exhibit the increment." (PMID 33519807, 2020).